MTOR (mechanistic target of rapamycin kinase)
Diseases named in the same sentence as MTOR in open-access papers (continued):
Sharing a sentence is not in itself a finding about the gene and the disease.
glioma (continued). "And among PI3K-Akt-mTOR pathway inhibitors, Temsirolimus was preferred over Everolimus for patients with high-risk glioma." (PMID 35756610, 2022). "Further biological experiments have shown that AdipoR2 overexpression inhibits glioma cell proliferation through the adenosine monophosphate associated protein kinase (AMPK)–mammalian Target of Rapamycin (mTOR) signaling pathway." (PMID 36105407, 2022). "In glioma cells, downregulation of the Nrf2 expression by shRNA suppresses mTOR while causing the ATP deficit to activate AMPK, leading to Nrf2 inhibition of mTOR." (PMID 35805130, 2022). "Abnormal activation of PI3K/AKT/mTOR signaling has been implicated in tumor initiation, progression, and therapeutic resistance in glioma." (PMID 35690717, 2022). "The mTOR pathway has been implicated in nervous system tumorigenesis in inherited brain tumor predisposition syndromes and glioma." (PMID 34205611, 2021). "It is believed that the low response to these inhibitors is associated with loss of the tumor suppressor PTEN, which is usually deleted or mutated in gliomas and plays a critical role in maintaining neural precursor cells via activation of the mTOR pathway." (PMID 33762015, 2021). "CPZ inhibited the Akt/mTOR pathway in PTEN (phosphatase and tensin homolog)-null U-87MG glioma cells, with constitutively active Akt/mTOR pathway, causing cell cycle arrest and autophagic cell death." (PMID 34262651, 2021). "Sempervirine had a significant anti-glioma cellular effect, which was associated with sempervirine-induced cellular G2/M phase arrest and blockade of the Akt/mTOR signaling pathway, thereby triggering apoptosis and cellular autophagy." (PMID 34916946, 2021). "Further mechanism study implicated that JMJD2A activated the Akt-mTOR pathway and promoted protein synthesis in glioma cells via promoting phosphoinositide-dependent kinase-1 (PDK1) expression." (PMID 32256210, 2020). "The high level of JMJD2A in glioma was associated with a low level of H3K9me3 and H3K36me3 as well as hyperactivation of the Akt-mTOR signaling pathway." (PMID 32256210, 2020). "The mTOR gene is closely associated with the occurrence of various tumors, such as glioma, esophageal, and colorectal cancer." (PMID 33062677, 2020). "The abnormal signaling resulting from such mutations interacts with PI3K-Akt-mTOR pathways that promotes chemo-resistance and survival in gliomas." (PMID 32517694, 2020). "Expression of adhesion molecule on glia (AMOG) in AMOG deficient human glioma cells results in phosphorylation of Akt with subsequent activation of mTOR signaling." (PMID 33281551, 2020). "The goal of this study was therefore to identify magnetic resonance spectroscopy (MRS)-detectable metabolic biomarkers associated with IDHmut glioma response to the dual PI3K/(mTOR) inhibitor XL765." (PMID 31324855, 2019). "A recent study revealed that some recurrent gliomas were hypermutated and harbored driver mutations in the RB and Akt-mTOR pathways that bore the signature of temozolomide-induced mutagenesis after adjuvant temozolomide chemotherapy." (PMID 30898102, 2019). "Coincidently, by bioinformatic analysis, we found that both hsa_circ_0037251 and the 3′-untranslated region (UTR) of mTOR share miRNA response elements (MREs) of miR-1229-3p, which suggested an association between hsa_circ_0037251 and mTOR in glioma." (PMID 31875034, 2019). "It will be also interesting to explore the potential influence of 1400W on PI3K-Akt/mTOR system, a key signaling pathway mainly involved in modulating autophagy and is associated to malignancy grade of gliomas in our experimental system." (PMID 31226744, 2019). "eIF4E/4E-BP1 association controlled by PI3K/Akt/mTOR pathway is a critical step in the translation initiation making this pathway an interesting target for gliomas treatment." (PMID 31795417, 2019).
glioma (continued). "The studied IDH wild-type glioma cell lines with different known oncogenic mutations showed high mTOR activity, due to well-known characteristics of PTEN loss and/or PI3K/Akt hyper-activation." (PMID 30574020, 2018). "Significantly, AMPKα mutation or knockdown restored mTOR activation and cyclin D1 expression in glioma cells." (PMID 27532105, 2016). "Existing evidences have shown that mTOR hyper-activation is associated with glioma progression and chemo-resistance." (PMID 27532105, 2016). "Pharmacologic inhibition of mTOR using CCI-779 (temsirolimus) depleted VEGFR-2 protein levels in PTEN-deficient LN-308 glioma cells." (PMID 25682871, 2015). "In both studies, additional inhibition of either mTOR by rapamycin or PI3K/mTOR by PI-103 resulted in a sensitizing effect on PTEN mutated glioma cells towards HER1/EGFR inhibition by erlotinib." (PMID 26056598, 2014). "A pathway linking epidermal growth factor receptor to mTOR that was critically dependent on PKC has been described in glioma and the association of a mTOR homolog with PKC has been demonstrated in Saccharomyces cerevisiae." (PMID 23230440, 2012). "Imaging studies were accomplished using the PTEN-deficient gliomas model to evaluate the effects of P13K/mTOR pathway inhibition on tumor growth rates and cellularity." (PMID 21267448, 2011). "Thus, mTOR signaling has a dual role in the glioma microenvironment, where it is implicated in both tumor progression and neurological dysfunction." (PMID 41301687, 2025). "What is new here is the GBM-specific link: we show that OPCML loss is associated with elevated p-AKT/p-mTOR in glioma cells and that PI3K blockade normalizes these readouts, potentially linking a neural adhesion molecule with a canonical survival pathway in this disease context." (PMID 41561740, 2025). "The PI3K/AKT/mTOR pathway is associated with the development of glioma‐related epileptogenesis." (PMID 38641945, 2024). "Interestingly, the inhibition of mGluR1 signaling was associated with the downregulation of the PI3K/AKT/mTOR signaling pathway, indicating that mGluR1 affects glioma via this signaling pathway." (PMID 36817470, 2023). "In addition, the inhibition of mTOR polarizes glioma-associated macrophages/microglia towards a proinflammatory phenotype, preventing the pro-tumor phenotype with in vitro models." (PMID 37372982, 2023). "Based on the results in Section 3.5, cuproptosis may be a glioma risk factor associated with the PI3K/AKT/mTOR pathway." (PMID 37515314, 2023). "Western blot results of biomarkers associated with the AMPK/mTOR pathway in glioma stem cells are consistent with those in glioma cell lines: pathway alterations by MDHDH could be reversed by PSMA1 downregulation." (PMID 36527092, 2022). "Targeting the PI3-kinase-Akt-mTOR signaling pathway with the mTOR small molecule inhibitor everolimus has also shown promising efficacy in a phase II clinical trial for children with recurrent/progressive NF1-associated low-grade gliomas." (PMID 35945463, 2022). "Additionally, the mTOR signaling pathway activation associates with the autophagy inhibition, supporting the glioma stem cell proliferation and pluripotency." (PMID 33525678, 2021). "Glioma development is also associated with mTOR hyperactivation." (PMID 34205611, 2021). "The results suggested that the anti-glioma effect was associated with autophagy and mTOR signaling." (PMID 32817393, 2020). "Since AKT/mTOR signaling is associated with cell migration, it may explain the high migration of IDH1Mut glioma cells." (PMID 33221817, 2020). "The effect of bortezomib on glioma cells may be mediated by the PTEN/PI3K/AKT/mTOR signalling pathway, causing activation of the apoptotic pathway." (PMID 32126150, 2020).
glioma (continued). "Mutations or deletions in the PTEN gene commonly lead to activation of the phosphoinositide 3-kinase (PI3K)/protein kinase B (AKT/PKB)/mammalian target of rapamycin (mTOR) signaling network and have previously been reported to be associated with reduced survival of glioma patients." (PMID 25682871, 2015). "Additionally, our laboratory is currently seeking to exploit recent findings that suggest crosstalk between the BRAF and PI3K/mTOR signaling pathways as driving mutations in pediatric gliomas." (PMID 23717811, 2013). "Furthermore, a rapamycin phase I trial was conducted in recurrent glioma patients deficient in PTEN based on preclinical data where PTEN mutant/null tumors exhibited an enhanced susceptibility to mTOR inhibition." (PMID 22530122, 2012). "The PI3K/Akt/mTOR signaling pathway is a frequently disrupted pathway across different cancer types, and abnormal activation of this pathway has been associated with tumor development, progression, invasion, and metastasis and is indeed activated in glioma cells." (PMID 38203743, 2024). "Thus, activation of the mTOR molecular cascade is observed in glioblastomas and it could be a trigger for glioma-associated epilepsy." (PMID 38067243, 2023). "Similarly, VM structures have been linked to mTOR expression in glioma cells." (PMID 34204169, 2021). "Therefore, we believed that the reason for the inhibition of glioma cell proliferation with ARG might be mediation by AKT/mTOR caused by autophagy." (PMID 33015162, 2020). "Thus, measurement of 2HG by magnetic resonance spectroscopy could be useful as a metabolic biomarker for mutations in isocitrate dehydrogenase 1 (IDHmut) glioma response to PI3K/mTOR inhibition." (PMID 31817676, 2019). "Furthermore, mTOR signalling is readily observed in clinical samples of IDH1-mutated gliomas." (PMID 27624942, 2016). "Everolimus (C53H83NO14) is a derivative of Rapamycin (sirolimus) and inhibits the activation of the mammalian target of Rapamycin (mTOR), which can be used for low- and high-grade gliomas." (PMID 41596345, 2026). "The phosphoinositide 3-kinase (PI3K)/protein kinase B (Akt)/mammalian target of rapamycin (mTOR) signaling cascade plays a pivotal role in regulating the proliferation, survival, and metabolic processes of cancer cells, particularly gliomas." (PMID 40075568, 2025). "All these confirmed the role of the AMPK/mTOR signaling pathway in metformin anti-glioma, suggesting its potential application prospects." (PMID 39944825, 2025). "Mechanism-wise, it inhibits the proliferation, invasion, migration, apoptosis, and cycle distribution of glioma cells by regulating the PI3K/Akt/mTOR signaling pathway." (PMID 40076568, 2025). "TREM1 shows significant enrichment in aggressive GBM subtypes and its inhibition functionally mediates anti-tumor effects by suppressing the glioma proneural-to-mesenchymal transition through modulation of the TLR4/PI3K/AKT/mTOR pathway." (PMID 41394801, 2025). "PI3K/AKT/mTOR signalling is involved in cancer progression by promoting the proliferation of glioma cells." (PMID 40527011, 2025). "The dual inhibitors AZD8055, Sapanisertib (INK128), and Torin-1 achieve more comprehensive mTOR inhibition and exhibit antitumor efficacy in preclinical glioma models." (PMID 41301687, 2025). "As gliomas have a notably aberrant PI3K/AKT/mTOR pathway, it is actively being pursued as a target for inhibitors." (PMID 40527011, 2025). "Inhibition of SOAT1 regulates SLC40A1 through the PI3K/AKT/mTOR pathway, elevating the level of lipid peroxidation in glioma cells and enhancing their sensitivity to ferroptosis inducers and radiotherapy." (PMID 40583858, 2025). "Our findings that SERPINB6 drives glioma progression via PI3K/AKT/mTOR‐mediated EMT align partially with its roles in other cancers, yet also highlight glioma‐specific mechanisms." (PMID 40665565, 2025).
glioma (continued). "Despite promising preclinical evidence, no clinical trials have directly evaluated neurologic outcomes such as seizure control, cognition, or neurological deficits in glioma patients receiving mTOR inhibitors." (PMID 41301687, 2025). "In murine glioma models, peritumoral neurons exhibit mTOR hyperactivation as evidenced by increased phosphorylation of ribosomal protein S6." (PMID 41301687, 2025). "In the context of diffusely infiltrating gliomas (glioma) and other brain tumors, mTOR signaling influences both tumor biology and the surrounding neuronal environment." (PMID 41301687, 2025). "In a previous study, we demonstrated that CAMK1D exerts a significant influence on glioma cell invasion through the phosphatidylinositol-3-kinase/protein kinase B/mammalian target of rapamycin (PI3K/AKT/mTOR) signaling pathway." (PMID 41050075, 2025). "Given the aberrant expression of JMJD2A and its involvement in the Akt-mTOR pathway, which aligns with our research focus on the effects of TB on glioma cell cycle regulation, we aimed to intensively study methylstat for its potential as a glioma therapeutic." (PMID 41011214, 2025). "This review synthesizes current knowledge of mTOR signaling across tumor and neuronal compartments in diffusely infiltrating glioma and highlights its potential as a therapeutic target at the intersection of cancer biology and neuroscience." (PMID 41301687, 2025). "Proteins in the PI3K/AKT/mTOR pathway are abnormally expressed in various tumours, including glioma, leading to malignant progression." (PMID 40665565, 2025). "In glioma cells, overexpression of Bcl-2 has been shown to suppress autophagy mediated by the Beclin1 and Akt-mTOR pathways." (PMID 40535121, 2025). "Most critically, SERPINB6 induces EMT and enhances the malignancy of glioma by activating the PI3K/AKT/mTOR pathway, suggesting its potential as a target in glioma treatment intervention." (PMID 40665565, 2025). "Previous evidence suggests that JMJD2A demethylates H3K9 and H3K36, thereby activating PDK1 expression and subsequently stimulating the Akt-mTOR pathway to promote glioma growth." (PMID 41011214, 2025). "In diffusely infiltrating gliomas, including glioblastomas, mTOR signaling is frequently dysregulated and contributes to malignant progression, therapeutic resistance, and metabolic adaptation." (PMID 41301687, 2025). "Despite considerable preclinical interest in targeting the mTOR pathway in glioma, clinical trials using mTOR inhibitors have demonstrated limited efficacy in slowing tumor progression." (PMID 41301687, 2025). "Recent studies also show its upregulation in glioma, where it drives tumor cell proliferation via Akt-mTOR pathway activation." (PMID 41011214, 2025). "Guo and colleagues illuminated its impact on glioma cell proliferation, motility, and apoptosis, revealing that the compound’s inhibitory action on glioma is mediated by modulating the mTOR signaling pathway, thereby triggering tumor cell apoptosis." (PMID 40076568, 2025). "A Western blotting analysis demonstrated that 3 significantly reduced the expression of p-Akt and p-mTOR in orthotopic glioma tissues." (PMID 40076568, 2025). "Polyamide amine dendrimers induced an increase of autophagy flux in human glioma cells through Akt/mTOR/p70S6K pathway, leading to abnormal accumulation of autophagosomes and neurotoxicity." (PMID 41142426, 2025). "During the development of glioma, metformin leads to the phosphorylation of acetyl-CoA carboxylase by activating the AMPK signaling pathway, resulting in the blocking of mTOR and inhibiting the growth of glioma." (PMID 39944825, 2025). "Title 4 will elaborate on how metformin activates the AMPK/mTOR signaling pathway to inhibit glioma formation." (PMID 39944825, 2025). "Collectively, these findings underscore the multifaceted role of mTOR signaling in glioma biology, encompassing tumor growth, progression, and therapeutic resistance." (PMID 41301687, 2025).
glioma (continued). "The efficacy of GRP78-targeted therapy can be assessed by evaluating the activation status of the AKT/mTOR signaling pathway in gliomas." (PMID 40002794, 2025). "In neurological roles, hnRNPH1 impacts normal brain development, modulates methamphetamine sensitivity (associated with genetic variants), and promotes glioma development via TRF2 splicing and Akt/mTOR pathway activation." (PMID 40507967, 2025). "Emerging evidence has revealed that gliomas reprogram peritumoral neurons through mTOR-dependent mechanisms, contributing to tumor-induced neurological dysfunction." (PMID 41301687, 2025). "Beyond tumor-intrinsic effects, recent evidence reveals that gliomas actively reprogram peritumoral neurons via mTOR-dependent mechanisms, leading to synaptic remodeling, hyperexcitability, and neurological symptoms such as seizures and cognitive dysfunction." (PMID 41301687, 2025). "The study on the activation of the AMPK/mTOR signaling pathway by metformin to inhibit glioma formation has achieved a series of important results at home and abroad." (PMID 39944825, 2025). "In this manner, NEAT1 functioned as an inhibitory factor on mTOR, thereby facilitating glioma tumorigenesis through the miR‐185‐5p/DNMT1/mTOR signalling pathway." (PMID 40387409, 2025). "This review aims to provide a comprehensive overview of mTOR’s contributions to glioma biology and tumor-induced neurological dysfunction." (PMID 41301687, 2025). "High expression of FZD1, 2, 5, 6, 7, and 8 correlates with oncogenic mTOR signaling and poor prognosis in gliomas." (PMID 40430278, 2025). "Among them, the PI3K/AKT/mTOR pathway is the crucial pathway highly involved in cell proliferation, growth, migration and cell cycle arrest in glioma." (PMID 38864445, 2024). "Fucoxanthin induces apoptosis to glioma cells via inhibiting PI3K/Akt/mToR cascade at high concentration upto 100 μM but increases cell viability at a lower concentration of 6.25 μM." (PMID 39407193, 2024). "Western blotting was used to investigate the effect of PDZK1 knockdown on the AKT1/mTOR signaling pathway in glioma cells." (PMID 38669103, 2024). "The phosphoinositide 3-kinase (PI3K)/protein kinase B (PKB or AKT)/mammalian target of the rapamycin (mTOR) pathway is often dysregulated in gliomas, leading to unregulated cell growth and survival." (PMID 39597073, 2024). "The lncRNA KB-1460A1.5 regulates TSC1 expression by sponging miR-130a-3p and participates in miR-130a-3p/TSC1/mTOR/YY1 feedback loop to inhibit glioma tumorigenesis." (PMID 38725030, 2024). "AT13148, CZC24832 and rapamycin were all PI3K/AKT/mTOR inhibitors and rapamycin had been reported to suppress glioma cell growth by inhibiting PI3K‐Akt–mTOR signaling." (PMID 38685685, 2024). "The regulatory factors that have been found to be associated with glioma include Phosphatase and Tensin Homolog (PTEN), Epidermal growth factor receptor (EGFR), ATG family, Beclin1, and Mammalian target of rapamycin (mTOR)." (PMID 38304870, 2024). "Mouse models have contributed to our understanding of OPG formation and have highlighted mechanisms for mTOR-dependent glioma formation, implicating microglia in glioma formation, and the presence of glioma-specific stem cells." (PMID 38804352, 2024). "Knocking down PDZK1 led to cell cycle arrest and cell apoptosis by inhibiting the AKT/mTOR signaling pathway in glioma cells." (PMID 38669103, 2024). "It induces ferroptosis in glioblastomas by inhibiting the AKT/mTOR/4EBP1 axis, and administration of fatostatin by nanoparticles resulted in the inhibition of glioma growth in an intracranial xenograft mouse model." (PMID 39062119, 2024). "Overexpression of H19 promotes the proliferation and migration of glioma cells, and H19 promotes the proliferation and autophagy of glioma cells through the mTOR/Unc-51-like autophagy-activating kinase 1 (ULK1) pathway." (PMID 38481525, 2024).